ENSG00000251715
Gene: Small nucleolar RNA gene on chromosome 13 (72,460,519 to 72,460,601, reverse strand). Ensembl gene ENSG00000251715.
Gene Ontology:
Biological process: RNA processing
Cellular component: nucleolus
Homologues: Paralogues in human: SNORA68 (67% identical), SNORA68B (66% identical).